CD9 (CD9 molecule)
Diseases named in the same sentence as CD9 in open-access papers (continued):
Sharing a sentence is not in itself a finding about the gene and the disease.
cancer (continued). "Among the 33 mammalian members of the Tetraspanins family, at least five of them, CD9, CD37, CD82, CD151 and TSPAN8, are reported to display altered expression in cancers when compared to normal tissues." (PMID 28423546, 2017). "In humans, anti-CD9 and CD63 antibodies cannot selectively attach to cancer-derived EVs, so further investigations are needed." (PMID 29238879, 2017). "It is important to note that similar SPR signals were observed during CD9 and/or CD63 capture for both cancer and healthy patient samples." (PMID 27464736, 2016). "CD9, CD63 and CD81 are expressed in many different types of cells including neural cells, cancer cells and cancer stem cell lines." (PMID 25682864, 2015). "Notably, CD9, as a cancer stem cell marker, may also be applied to human malignant mesothelioma." (PMID 24520284, 2014). "The cell surface expression of other tetraspanin members that play prominent roles in cancer cell invasion including CD63, CD81, and CD151 were unaffected by CD9 overexpression." (PMID 23840773, 2013). "The panel of antibodies contained the well-known exosome markers (CD9, CD63, CD81 and HLA-ABC) and 17 other membrane markers and antigens related to, for example, cancer and inflammation." (PMID 26082317, 2013). "By employing RT-PCR and immunohistochemistry, we studied the expression of CD9, CD63 and CD82 in 49 paired tissue specimens of normal gastric mucosa and carcinoma." (PMID 21521534, 2011). "Although the mechanisms of action of the transmembrane superfamilies, motility-related protein-1 (MRP-1/CD9) and KAI1/CD82, are not well known, they are reported to suppress the metastasis of several kinds of cancers." (PMID 10098753, 1999). "Our findings build on this emerging evidence and suggest that PTGFRN may serve as a pan‐cancer marker of EVs derived through non‐canonical, ESCRT‐independent pathways—distinct from the classical CD9‐, CD63‐, or CD81‐marked small EVs." (PMID 41039818, 2025). "Western blotting revealed CD9, CD81, and CD63 in normal and cancer Exos." (PMID 39206404, 2024). "Moreover, CD9 was enriched in “immune system;” CD63 was enriched in “transport and catabolism” and “cancers: overview;” CD81 was enriched in “infectious diseases: parasitic,” “infectious diseases: viral” and “immune system” by KEGG pathway analysis." (PMID 38725025, 2024). "The increased expression of CD133, CD9, and CD44, along with SOX9, TUBB3, MGMT, and ABCG2, may have led the GBMs on a path of acquiring cancer-specific stemness." (PMID 36834653, 2023). "Altogether, TSPAN1, TSPAN15, TSPAN29, and CD151 could support cancer cell growth, while TSPAN31, TSPAN6, CD9, CD37 could inhibit cancer growth." (PMID 36941633, 2023). "This is particularly interesting because CD9(+) sEVs have been implicated in a variety of pathological conditions, including cancer and infectious diseases, suggesting that CD9 is not merely a surface tetraspanin for sEVs." (PMID 37371093, 2023). "Along with the upregulated CD9 levels on exosomes, the authors also found that αvβ3 integrin was also expressed in plasma exosomes of cancer patients, but the expression of another classic tetraspanin CD81 decreased somehow in cancer patients." (PMID 35757760, 2022). "In CRC, the SNP rs11064124G > A in a cancer-specific SE at 12p13.31 promotes its binding affinity to vitamin D receptor (VDR), resulting in the greatly reduced expression of the tumor suppressor genes CD9 and PLEKHG6, which leads to cancer cell proliferation." (PMID 35277481, 2022). "WB results validated the expression of EVs specific markers and cancer specific marker, we obtained distinct bands for CD9, TSG101 and PDL-1 verifying the presence of the EVs specific markers and cancer specific marker, respectively, while calnexin as an EVs’ negative marker." (PMID 35624582, 2022). "In particular, high CD9 expression was observed in sparse highly pigmented cells, while small pigmented cancer cells were weakly or not stained." (PMID 35563166, 2022).
cancer (continued). "So far, very few studies have investigated three tetraspanins (CD63, CD9, and CD81) together in clinical settings; therefore, it is still unclear whether the level of CD9, CD63, or CD81 correlates with different types of cancers." (PMID 35757760, 2022). "In BPH, moderate or intense staining was observed whereas the expression of CD9 in cancer tissue was almost mild or absent." (PMID 35204378, 2022). "CD9 proteins are also expressed on the surface of MSCs and MSC-derived exosomes; however, to our knowledge, there has been no report about the effect of MSCs’ exosomal CD9 on cancer cell migration." (PMID 33572290, 2021). "Interestingly, this study also illustrated that CD9 promotes plasma membrane localization of the glutamine transporter ASCT2 and further increases uptake of glutamine, an essential metabolite for cancer progression, in PDAC cells." (PMID 33912458, 2021). "This system efficiently identified characteristic CD9, CD44 and epithelial cell adhesion molecule (EpCAM) surface proteins, demonstrating that it could be used for cancer diagnosis and cell phenotype characterization." (PMID 34440265, 2021). "And the prognosis of patients with positive CD9 in cancer and/or stromal cells was worse than the patients with dual CD9-negative expression." (PMID 34222025, 2021). "Nevertheless, studies have shown that CD9 expression is not consistent with the prognosis of cancer patients." (PMID 34493282, 2021). "The data from this study convincingly show that plasma exosome concentration in patients is altered depending on medical history and that cancer, HIV immunopositivity, as well as systemically administered chemotherapy can influence the levels of CD9-posistive plasma exosomes." (PMID 34680341, 2021). "For the specific characterization by flow cytometry and confocal microscopy, different commercial antibodies against selected receptors were used, including the general tetraspanins CD9, CD63 and CD81, and cancer-related receptors (CD24, CD44, CD54, CD326 and CD340)." (PMID 32054015, 2020). "Cancer-associated exosomes opt to transport specific transmembrane proteins, including integrins and tetraspanins such as CD9, CD63, CD81, and CD82 that are specifically recognized by target cells, which can explain the high rate of exosomal uptake by cancer-adjacent stromal cells." (PMID 32121073, 2020). "There is very little known about the functional role of miR-518f-5p in any cancer, or how CD9 levels are regulated in non-tumorigenic and tumorigenic breast cells." (PMID 32224917, 2020). "Some previous studies have shown that CD9 and CD81 are involved in cancer." (PMID 32350244, 2020). "Facilitated by CD9 antibody (for exosome capture), CA-125 (for ELISA detection), EpCAM (for ELISA detection), and CD24 antibodies (for ELISA detection), this platform enabled rapid exosome isolation and in situ non-invasive cancer detection." (PMID 32206116, 2020). "Cancer EVs normally have the same set of surface markers to those of healthy cells, being indistinguishable from their normal counterparts, although CD9 and CD81 overall seem to be more abundant, but mutually exclusive, on cancer EVs." (PMID 31877735, 2019). "In addition, there was also a CD9 dependent increase in MDR1 and BCRP; both of which are ABC transporters that have been shown in other cancer models to confer multidrug resistance to chemotherapies such as Dox and 5FU." (PMID 31191817, 2019). "Among them are genes involved in cell adhesion/migration processes (PEPD), migratory potential of cancer cells (ACTN1), ECM (LTBP2, PRG4, ADGRL1, CD9), or in metabolic processes (LDHD, ALDH7A1), as well as proto-oncogenes or their ligands/inhibitors (FYN, PPP1R13L)." (PMID 30838002, 2019). "Furthermore, more in-depth studies are required as anti-CD9 and CD63 antibodies are unable to selectively target the cancer-derived EVs in humans." (PMID 31428232, 2019).
cancer (continued). "They analyzed the expression of three exosomal markers (CD9, CD81, and CD63), showing a mean concentration higher for CD63 and lower for CD9 and CD81 between cancer patients and healthy individuals, although significant statistical differences were observed only for CD81 levels." (PMID 29890622, 2018). "In that study, EVs tagged by anti-CD9 and CD63 were internalized by macrophages via phagocytosis before they could promote cancer progression." (PMID 29238879, 2017). "Second, both CD9 and importin β1 were found in N-ALE and nuclei of cancer cells." (PMID 28129640, 2017). "The formation of CD9-dependent microvilli zippers is not unique to cancer cells since similar structures have been demonstrated to regulate virus-induced cell fusion." (PMID 25762645, 2015). "Similar results were obtained in A431 carcinoma cells, indicating that the ability of CD9/CD81 to regulate α3β1 integrin is not restricted to the MDA-MB-231 model." (PMID 23613949, 2013). "Second, there were cancer-related genes, such as CD9 and CALMODULIN, which were not known to be HuR regulated until this report." (PMID 20370918, 2010). "Of the 146 colon cancers studied, 82 carcinomas (43.8%) were evaluated as MRP-1/CD9-positive and 64 carcinomas (56.2%) as MRP-1/CD9-negative expression." (PMID 12838318, 2003). "Thus, p-blinatumomab effectively targets cancer antigens expressed in ALL, such as CD9 and CD3ε." (PMID 41168302, 2025). "Notably, while tetraspanins were often used as markers for sEVs, significant signals in CD63 and CD9 were detected in cancer cell-derived m/lEVs, suggesting that these molecules are not unique markers for sEVs, as the MISEV 2018 guidelines stated." (PMID 36992223, 2023). "By interacting with various partners, the negative or positive effects of CD9 on cancer cells could depend not only on its own expression level, but also on its binding proteins." (PMID 36010551, 2022). "The separationwas driven primarily by CD9 (importance = 0.37), TENX (importance= 0.32), and di-N-acetylchitobiase (DIAC, importance = 0.28), withboth TENX and DIAC showing a downregulation with disease progressionand CD9 showing a stronger upregulation in early- than late-stagepancreatic cancer." (PMID 35605973, 2022). "However, reports on the effect of the CD9 of MSCs or MSC-derived exosomes on cancer cell migration are still lacking." (PMID 33572290, 2021). "Therefore, our results indicated that reduced expression of CD9 and CD81 in HCC may activate JNK signaling pathway, which promotes cancer cell proliferation via regulating the downstream genes such as Cyclin D1 and Bcl-2." (PMID 32350244, 2020). "Interestingly, CD9 is considered as a suppressor of metastasis in a variety of cancers, including breast, non-SCLC, colon, and myeloma, although it was shown to promote malignancy in other cancer types." (PMID 30736372, 2019). "This rarely explored phenomenon may explain why CD9 function in various cancer cell lines is not fully congruent." (PMID 23840773, 2013). "In general, the EV levels of CD9, CD81 and CD151 were increased in OC and B samples compared with Ctrl and PD samples, which could be due to samples being obtained from two different biobanks, but increased levels of EVs have previously been reported in cancer patients." (PMID 40372993, 2025). "Furthermore, our study identified that the prevalence of tetraspanin+ EVs did not significantly differ between cancer patients and healthy individuals, and that the majority of CD9+ EVs, the most abundant subpopulation of tetraspanin+ EVs in body fluids, derive from non‐cancerous cells." (PMID 36973758, 2023). "Thus, EV CD9/CD63 expression ratio, but not EV physical characteristics, may help differentiate NSCLC patients from cancer-free high-risk individuals." (PMID 35461372, 2022).
cancer (continued). "A multitude of evidence revealed that distinct exosomal proteins, e.g., Rab, GTPases, ESCRT, CD9, CD81, CD63, flotillin, TSG101, ceramide, Alix, tetraspanins, and integrins, could be used for cancer detection and consideration of clinical outcomes in cancer patients." (PMID 33168028, 2020). "However, this experiment strategy of targeting human CD9 and CD63 is only applicable in a xenograft nude mouse model for selectively eliminating human cancer sEVs from the blood, since CD9 and CD63 are expressed in sEVs released from both noncancerous and cancerous cells in humans." (PMID 32847103, 2020). "sEV enrichment was verified by transmission electron microscopy and western blotting using antibodies against ALIX, TSG101, CD63, CD81, CD9 (sEV markers), and also against GRP94 (negative control), HSP70 (cancer biomarker), and PD-L1." (PMID 37973956, 2024). "Although these reports did not clarify how the suppression of CD9 expression inhibits EV uptake in cancer cells, they identified CD9 function as a mediator of the internalization of CAF-derived EVs into cancer cells." (PMID 36424598, 2022). "We found that CD9 was co-expressed with CD63-enriched UEVs, but not the CD47, which is over-expressed on EVs derived from cancer cells and involved in cancer metastasis." (PMID 34349163, 2021). "Exosomes derived from MSCs express “CD63, CD9 and CD81” to elicit TRAIL-mediated apoptosis in cancer cells in a dose-dependent fashion without cytotoxicity to human bronchial epithelial cells." (PMID 32957534, 2020). "By applying a RNA sequencing (RNA-seq) approach, we found that the expression of only 15 transcripts was altered upon short exposure (4.5 h) of MSCs to EVs derived from cancer FEMX-I cells, but not (or to a lesser extent) to CD9-depleted EVs." (PMID 28129640, 2017). "Three non-cancer healthy control individuals who did not receive the survivin immunogen were also assessed for survivin and GFAP expression on CD9+ exosomes (bottom row)." (PMID 29383115, 2017). "The expression of both MRP-1/CD9 and KAI1/CD82 were positive on the cell membranes of normal oesophageal epithelial cells, but reduced or negative in the cancer cells." (PMID 10098753, 1999). "Moreover, macrophages were utilized to internalize the EVs tagged by anti-CD9 and CD63 and were not allowed to promote cancer progression." (PMID 31428232, 2019). "While the small number of cancer samples did not allow assessment of statistical significance, several of the new markers identified through mRNA analysis also showed trends of increased protein expression in SQCCs relative to ADCs (CD71/TFRC, CD9, PDPN, CD138/SDC1, CD99)." (PMID 25551685, 2014). "Materials and methods: A novel protein array based on biotin-labelled anti-tetraspanin (CD9, CD63 and CD81) antibodies specific for exosomes in general enabled capture of exosomes from crude human donor plasma and MV preparations from stable isotope-labelled cancer cells and synovial fluid." (PMID 26082317, 2013).
infection (83 papers, 2007 to 2026). The state of being infected such as from the introduction of a foreign agent such as serum, vaccine, antigenic substance or organism. "According to a previous study, the expression of CD9 was induced by pathogenic infection, which indicates that CD9 participates in the teleost immune response." (PMID 33597018, 2021). "Increasing evidence indicates that CD9 in mammals participates in the immune response to pathogenic infection." (PMID 33597018, 2021). "Studies have also revealed that CD9-enriched exosomes enhance viral uptake by recipient cells and promote susceptibility to infection." (PMID 33348699, 2020). "Our results are in agreement with role of another tetraspanin molecule CD9 that has been shown to render MDBK cells susceptible to infection by a canine distemper virus (CDV) and predicted that this molecule serves as the entry molecule." (PMID 17572908, 2007). "Moreover, studies of the responses of CD9 isoforms to pathogenic infection are limited." (PMID 33597018, 2021). "Thus, to strengthen the conclusion that the CD81 A and B helices in a CD9 backbone are sufficient to render HepG2-A16 cells susceptible to infection, CD81ccg9 and CD9ccg81 chimeras were stably expressed in HepG2-A16 cells and compared to cells stably expressing CD81." (PMID 18389082, 2008). "Comparative analysis using the MACSplex EV kit revealed a significant reduction in the tetraspanins CD63, CD81 and CD9 in sEVs derived from Salmonella-infected macrophages (obtained at 24- and 48- hours post-infection) relative to uninfected controls." (PMID 40895579, 2025). "In vitro stimulation with CD9+ CD81+ exosomes from DENV-2 NGC-infected cells favored the infection of naïve cells, indicating their ability to transmit virus." (PMID 39754219, 2025). "Unexpectedly, upon infection with the ΔpilT mutant strain, the accumulation of CD9 around bacterial colonies was much more abundant in PFA-fixed than in live cells, comparable to that observed in living cells infected with the 2C4.3 strain." (PMID 41290585, 2025). "To identify protein signatures on EVs that reflect active COVID-19 infection and to distinguish them from convalescent state, we compared the proteome of patients CD9+-EVs from all groups eight months after the peak of the infection (m8)." (PMID 39569406, 2024). "To identify SARS-CoV-2 peptides, we performed label-free liquid chromatography with tandem mass spectrometry (LC-MS/MS) analysis of EVs isolated by CD9 direct immunocapture at the peak of infection." (PMID 39569406, 2024). "In contrast, EMCV-LTMEV and EMCV-LSAFV did not prominently enhance the release of flotillin and LC3 at 7 or 10 hpi, although infection with EMCV-LTMEV increased the release of CD9 at 10 hpi." (PMID 38662794, 2024). "Infection with EMCV-2Apro enhanced the release of EVs carrying the tetraspanin CD9 and flotillin, resembling the EV subpopulation(s) induced by EMCV-Wt infection." (PMID 38662794, 2024). "Infection with a high inoculum of HIV increased the expression of the co-receptor CCR5, as well as the tetraspanins CD9 and CD81, which correlated with deficient osteoclastogenesis." (PMID 37404829, 2023). "Using a genetic approach, knockouts of CD9 in SupT1 cells had reduced expression of immediate early transcripts but deficiency for CD46 showed abolished binding and reduced infection in SupT1 cells." (PMID 33968023, 2021). "CD63 on progeny HIV-1 surface was also found to interfere with infection, and this interference was extended to other tetraspanins (CD9, CD81, CD82, and TSPAN7)." (PMID 34769038, 2021). "For example, infection with the viral pathogen VHSV significantly upregulated the expression of CD9 in rainbow trout." (PMID 33597018, 2021). "Conversely, depletion of CD9 in HaCaT cells led to a significant increase in the amount of released TGFα-AP, which again corresponds to the effect of CD9 siRNA on infection rates in these cells." (PMID 32385608, 2020).